FGD3 (FYVE, RhoGEF and PH domain containing 3)
Diseases named in the same sentence as FGD3 in open-access papers (continued):
Sharing a sentence is not in itself a finding about the gene and the disease.
epilepsy (1 paper, 2025). A brain disorder characterized by episodes of abnormally increased neuronal discharge resulting in transient episodes of sensory or motor neurological dysfunction, or psychic dysfunction. "We found that CDC25B, DNMT1, GZMA, MTX1, and SSH2 expression decreases epilepsy risk, whereas FGD3, RAF1, and SH3BP5L increase it." (PMID 39753851, 2025). "Notably, Cluster 3 microglia were only detected in the TLE group and were entirely absent in normal tissue, suggesting that this cluster represents an epilepsy‐specific microglial subpopulation with disease‐specific high expression of Fgd3." (PMID 39753851, 2025). "In our study, both FGD3 and SSH2 were significantly upregulated at the transcriptomic and proteomic levels in epilepsy." (PMID 39753851, 2025).
lung carcinoma (1 paper, 2022). "During our analysis, increased expressions of PCDH7, DEPDC1B, SATB2, and S100P were detected in lung cancer tissues and adjacent normal tissue of TCGA-LUAD patients, but expression of FGD3 was observed to be lower." (PMID 36530971, 2022).
metastatic tumors (1 paper, 2025). "Compared to normal breast tissue, FGD3 is highly expressed in both non-metastatic and metastatic tumors, but there is not a strong correlation between FGD3 level and tumor metastasis status." (PMID 41225536, 2025).
ovarian carcinoma (1 paper, 2025). A malignant neoplasm originating from the surface ovarian epithelium. "Of course, given the heterogeneity of these ovarian cancer cell lines, FGD3, while important, will only be one factor modulating sensitivity to ErSO-induced cell death." (PMID 41225536, 2025). "We compared FGD3 levels to sensitivity of 4 human ovarian cancer cell lines (IGROV-1, SK-OV-3, ES-2 and PEO4) to ErSO-induced cell death." (PMID 41225536, 2025). "Therefore, it was of interest to explore the effect of different FGD3 levels on sensitivity of ovarian cancer cells to ErSO." (PMID 41225536, 2025).
tumor (8 papers, 2017 to 2026). "An unpaired t test comparing FGD3 protein expression in N1 to N3 primary tumor samples with lymph node metastatic tissue samples suggests that lower FGD3 protein level indicates metastasis (P = .142)." (PMID 32913979, 2017). "Moreover, using KM method, we found that patients with low FGD3 expressing tumours had significantly reduced DFS (p = 0.042) and OS (p = 0.007)." (PMID 31645624, 2019). "Comparing top DEGs which differentiate dura-originating from tumor-originating T cells, dura T cells’ DEGs were related to T cell migration and function, such as CXCR3 and ITGAL, as well as cell motility genes SUSD3 and FGD3." (PMID 35534852, 2022). "However, the role of FGD3, TMEM176A, CD1B and MATK in anti‐tumor immunity remains unclear." (PMID 36814908, 2023).
cancer (7 papers, 2010 to 2025). A tumor composed of atypical neoplastic, often pleomorphic cells that invade other tissues. "Conversely, FGD3 overexpression increased cell membrane disruption and the cancer cell’s sensitivity to lytic cell death induced by doxorubicin, epirubicin and the other death inducers." (PMID 41225536, 2025). "Our study suggests FGD3 levels can be used to identify cancer patients most likely to benefit from doxorubicin, and other chemotherapy agents that induce cell swelling, PMR and ICD." (PMID 41225536, 2025). "Concerning DFS, patients diagnosed with cancer over 40 years of age and high FGD3 expression (n = 221) had fewer relapses than patients of the same age but with low FGD3 expression (n = 119)." (PMID 34359725, 2021). "Concerning disease-free survival, patients with early-stage cancer and high FGD3 expression (n = 227) had fewer recurrences than patients with tumors at the same stage but with low FGD3 expression (n = 103)." (PMID 34359725, 2021). "The FGD3 gene works as a cell migration inhibitor and seems to be a promising indicator of outcome in some human cancers including breast." (PMID 31645624, 2019). "The availability of a growing collection of cancer cohorts with outcome data has allowed for the confirmation of the clinical importance of FGD3 as a prognostic biomarker and implications that can guide treatment." (PMID 32913979, 2017). "From a genome-wide CRISPR screen with selection against ErSO, database analysis, ErSO-resistant mutants and studies in cells in culture, PDOs and mice, we identify FGD3 as a critical regulator for the decision of cancer cells undergoing cell swelling to proceed to PMR and lytic cell death." (PMID 41225536, 2025). "Notably, elevated FGD3 increased release of DAMPs, strongly enhanced exposure of immunogenic cell surface calreticulin and increased sensitivity of cancer cells to NK cell-mediated lysis." (PMID 41225536, 2025). "We then explored FGD3’s effect on cancer cell survival during longer-term ErSO-induced stress." (PMID 41225536, 2025). "This suggested FGD3 may play a role in the plasma membrane and cytoskeleton that controls a cancer cell’s ability to survive ErSO-induced rapid cell swelling." (PMID 41225536, 2025). "A PubMed search for FGD3 and cancer mentioned in the abstract resulted in one publication." (PMID 32913979, 2017). "The level of FGD3 strongly impacted whether cancer cells that undergo cell swelling and ATP depletion induced by several agents, FDA-approved aprepitant/EmendTM (necrosis inducer), shikonin (necroptosis inducer) and doxorubicin (pyroptosis inducer) proceed to PMR and cell death." (PMID 41225536, 2025). "Since FGD3 knockout strongly prevented the stressed cancer cells from ErSO-induced cell death in multiple contexts and FGD3 overexpression enhanced cell death, FGD3 level must impact the end-stage decision of whether stressed and swollen cancer cells proceed to PMR and lytic cell death." (PMID 41225536, 2025). "Ingenuity analysis identified a group of 7 genes (BEX1, FBLN1, FGD3, HBEGF, KLK3, KLK6, and WNT5B) related to cancer, cellular function and maintenance, cellular growth, invasion, as well as proliferation with P < 0.001-0.05." (PMID 21134280, 2010). "Taken together, these data demonstrate that FGD3 level correlates with the survival of stressed cancer cells without regulating the stresses contributing to cell death." (PMID 41225536, 2025). "Since we and others have found that compounds based on the ErSO chemical scaffold do not induce TRPM4 dependent cell swelling and lytic cell death in mouse cancer cells, we could not assess the effect of FGD3 on immunogenicity in syngeneic mouse models." (PMID 41225536, 2025).
skeletal dysplasia (2 papers, 2015 to 2017). Any Mendelian diseases that affects growth and development of the skeleton. "Here we show that CW-3 is linked inseparably with skeletal dysplasia and a non-synonymous variant of FGD3 causing a reduced activity of the encoding protein is a positional candidate QTN." (PMID 26306008, 2015). "Genomic analyses revealed that skeletal dysplasia is inseparably linked with CW-3 and a functional variant of FGD3 was identified as a positional candidate QTN." (PMID 26306008, 2015). "For example, the allele in the Acyl-CoA:diacylglycerol acyltransferase 1 (DGAT1) increases milk fat content and decreases milk yield in dairy cattle, and the risk allele FYVE, RhoGEF and PH domain-containing protein 3 (FGD3) of skeletal dysplasia increases carcass weight." (PMID 29132308, 2017). "This is the first report showing association of FGD3 with skeletal dysplasia." (PMID 26306008, 2015). "Therefore, generation and analyses of Fgd3-deficient mice may be crucial to verify the causality of Fgd3 for skeletal dysplasia." (PMID 26306008, 2015). "Only FGD3 has a non-synonymous coding variant within the critical region for skeletal dysplasia and the mutant protein showed reduced GEF activity, strongly suggesting that a mutation in FGD3 is causative." (PMID 26306008, 2015).
FGD3 also shares sentences with these, for which no sentence is quoted: lung adenocarcinoma (2 papers); Benign tumors (1); cervical cancer (1); cervical squamous cell carcinoma (1); endocervical adenocarcinoma (1); metastatic carcinoma (1); ovarian tumors (1); sarcoma (1); urothelial bladder carcinoma (1).